PIK3CA (phosphatidylinositol-4,5-bisphosphate 3-kinase catalytic subunit alpha)
Diseases named in the same sentence as PIK3CA in open-access papers (continued):
Sharing a sentence is not in itself a finding about the gene and the disease.
tumor (continued). "MiR-375 inhibits CRC tumour growth, migration and angiogenesis by targeting the CTGF/EGFR-induced downregulation of the PIK3CA-AKT and BRAF-ERK1/2 cascades, thereby acting as a tumour suppressor." (PMID 33865381, 2021). "In the HBCx-17 model (WT for PIK3CA), only the combination of BYL719 + fulvestrant inhibited tumor growth with a TGI of 64% (P = 0.03, Mann-Whitney t test), although no tumor regression was observed." (PMID 34020697, 2021). "We analyzed the effect of driver gene expression in the different subtypes and found that the expression of PIK3CA, PIK3R1, and PTEN was significantly lower in tumor samples than in normal samples." (PMID 34277633, 2021). "Several important genes emerged in this study that are overexpressed in BA versus WA patients in both tumor and TAS, including PIK3CA, mTOR and CD53." (PMID 34316327, 2021). "Among all the genes reported in the literature with their potential cause in tumor development, CPEB4, APC, TRIP13, EIF2S3, EIF4A1, IFNg, PIK3CA and CTNNB1 have particularly been identified to be a set of potential candidates for tumor development." (PMID 33237662, 2021). "In a large platform of patient-derived tumor xenografts (PDTX), Bertotti and colleagues showed a significantly higher prevalence of HER2 gene amplification in cetuximab-resistant RAS, BRAF, and PIK3CA wild-type tumors." (PMID 34202896, 2021). "We initially explored the expression of PIK3CA KIRC, which revealed that the mRNA and protein levels of PIK3CA were significantly lower in tumor tissues than in normal tissues." (PMID 34367282, 2021). "Defects of the PI3K-PTEN-AKT pathway, PIK3CA specifically, with a prevalence of approximately 6–21% in the whole-exome sequencing of HNSCC, with increased frequency in HPV-positive tumours, is another critical point in the carcinogenesis of the HNSCC." (PMID 34829777, 2021). "Defective PIK3CA has been documented by Whyte and Holbeck to enhance tamoxifen sensitivity in selected NCI60 tumor cell lines." (PMID 33909629, 2021). "On the contrary, other genes in the list (i.e., PIK3CA, PTEN, BRAF) are well-known tumor suppressor genes or oncogenes in many cancers." (PMID 34768773, 2021). "We found the co-occurrence of genetic mutations in tumors with PARP1 alterations to be involved with some genes such as KMT2D/2C as driver genes, PIK3CA, ARID1A, H3F3A, HIST3H3, RYR2, and thus, PARP1 alteration should promote tumor mutability." (PMID 34531868, 2021). "In mouse xenograft model of PIK3CA-mutant MKN1 GC cells, alpelisib combined with paclitaxel significantly enhanced anti-tumor activity by decreasing Ki-67 expression and increasing TUNEL expression." (PMID 32704014, 2020).
tumor (continued). "PIK3CA codes for p100α, the catalytic subunit of the PI3Kα complex, and phosphatase and tensin homolog (PTEN) is a tumor suppressor gene of this pathway that is frequently deleted in cancers." (PMID 33148288, 2020). "PIK3CA small interfering RNA (siPIK3CA) can selectively inhibit PIK3CA gene expression to block SCLC cell proliferation and inhibit tumor growth." (PMID 32178266, 2020). "Conversely, gain in KRAS, PIK3CA and SMAD4 alterations and scarce granzyme-B+ T-cells infiltration were observed when the tumor evolved towards a poly-metastatic spread." (PMID 33096795, 2020). "However, the EGFR T790M mutation, acquired RTK MET gene amplification and PIK3CA mutations, share the same effect of reestablishing the downstream PI3K/AKT/mTOR pathway in the presence of the anti-EGFR inhibitors, ultimately converting a TKI-sensitive tumor into a TKI-resistant tumor." (PMID 33123479, 2020). "In the PIK3CA mutant model (HBCx-154), treatment with the three PI3K pathway inhibitors resulted in a significant inhibition of tumor growth (TGI= 80% for BAY-80-6946, p=0.006, 72% for PF-04691502 and AZD2014, p=0.02 and p=0.01, respectively)." (PMID 32042320, 2020). "Not surprisingly, we find that the 105C mutational profile matches that of many OCCC cell lines and human tumor samples with respect to the ARID1A, PIK3CA, and PTEN genes." (PMID 33153119, 2020). "These genes stimulated PTEN/PIK3CA/AKT pathway, which in turn would lead to increased proliferation of tumor cells." (PMID 33996530, 2020). "Copy number gain of PIK3CA was present in all three PDX models, as well as AKT1 in TC1 and TC4 PDX tumours." (PMID 33144587, 2020). "Using a mouse xenograft model of PIK3CA-mutant MKN1 cells that stably express luciferase, the in vivo anti-tumor activity of alpelisib and paclitaxel combination was evaluated." (PMID 32704014, 2020). "Among the 550 patients of the BOLERO-2 trial with plasma samples taken at the start of treatment to analyse circulating tumour (ct)DNA, median PFS of patients carrying wild-type or mutant PIK3CA was similar in the combination and the placebo arm." (PMID 32566979, 2020). "Univariate analysis by Kaplan–Meier survival analysis and log-rank test was performed using several factors, including age, primary tumour site, histological grade, histological type, KRAS, BRAF, PIK3CA and MSI status." (PMID 31406299, 2019). "Amplification of KRAS, PIK3CA, SMARCB and PDFGRA was detected in 1 poorly differentiated carcinoma and in 3 INT-type tumours, respectively." (PMID 30837681, 2019). "Correlation analysis using available clinicopathological information revealed that PIK3CA H1047R and BRAF V600E MFs correlate positively with maximum tumor dimension." (PMID 30813596, 2019). "Patients were diagnosed with 29 tumor types and harbored alterations in 43 oncogenes, most commonly ERBB2 (21.3%), PIK3CA (14.1%), and BRAF (8.7%)." (PMID 32914018, 2019). "Among all variants, four recurrent substitutions are shared (MAPK1 E322K, PIK3CA E542K and E545K, and FBXW7 R505G) and have similar selection intensities within the two tumor types." (PMID 30647454, 2019). "Taking advantage of the tumor-specific inference capability of TCI analysis, we identified the target DEGs regulated by each SGA event affecting PIK3CA (either SM or SCNA) in individual tumors." (PMID 31276486, 2019).
tumor (continued). "This suggests that alteration in YAP/TAZ upstream regulators (i.e., FAT1 and PIK3CA in HNSCC) takes place during HNSCC tumor progression leading to the activation of these two co-transcriptional factors and their target genes." (PMID 31817001, 2019). "Taken together these data suggest that PIK3CA p110α inhibition with BYL719 suppresses AKT and has anti-tumor activity." (PMID 31235758, 2019). "The authors went on to show that combinations of XL147 with HER2 antagonists (trastuzumab or lapatinib) were synergistic in delaying tumour growth in mice bearing xenografts derived from BT474, a HER2+/PIK3CA-mutant BC cell line." (PMID 35582276, 2019). "Given that PIK3CA and AKT1 genes promote proliferation and survival of tumor cells, their down-regulation by miRNAs results in a decline in the proliferation of cancerous cells." (PMID 34466540, 2019). "We conclude that the decreased tumor growth observed in the treatment groups is indeed based on the efficient downregulation of the intended and oncogenic factors KRAS and PIK3CA driven by an antibody-directed esiRNA delivery." (PMID 30001368, 2018). "Signal transduction of PIK3CA via the kinases AKT and mTOR has been well documented in tumor growth and angiogenesis." (PMID 29985963, 2018). "Treatment of the tumor-derived cells with AZD8835 or GDC0941, two PIK3CA selective inhibitors, had minor pro-apoptotic effects compared to vehicle-treated cells." (PMID 29951225, 2018). "To validate that DANCR/RXRA/PIK3CA signaling pathway regulates TNBC tumor growth, we down-regulated RXRA and overexpressed PIK3CA in MDA-MB-231 and MDA-MB-468 cells with a RXRA shRNA or a PIK3CA vector." (PMID 30518934, 2018). "When correlated to tumor progression markers, a slight significant correlation was seen between estrogen receptor and PTEN (IHC and FISH), estrogen receptor and PIK3CA (IHC) as well as between progesterone receptor and PIK3CA (IHC)." (PMID 29739401, 2018). "In this study, we found the well-known driver genes MAPK1, PIK3CA and SMAD4 to be private to either the primary tumour or the metastasis." (PMID 30029640, 2018). "Pre-clinical data indicate that tumors with PIK3CA mutations or PTEN loss are more sensitive to PIK3CA and AKT inhibition but the value of these markers in clinical practice is uncertain due to the complexity of the pathway and unknown effects of these agents on the tumor microenvironment." (PMID 28420128, 2017). "Even when the breast PIK3CA H1047R data point (log10 MF standard deviation = 1.2418; COSMIC tumor prevalence = 13.5%) was removed from the analysis, a strong correlation was observed (r = 0.6679, P = 0.0065)." (PMID 28755461, 2017).
tumor (continued). "Similarly, a PIK3CA p.Y207* mutation detected only in serial cfDNA samples from MYL-001 likely represents a real tumour-derived mutation not adequately represented in the localized BM aspirate used for comparison or originating from the metastatic tumour sites." (PMID 28492226, 2017). "Here, we have demonstrated that the use of specific inhibitors to the pathways which we identified as induced in PIK3CA‐mutant tumors, such as STAT3, β‐catenin, and IGF‐1R, potentiates the cytotoxic effect of PI3K inhibitor on mutant PIK3CA tumor cells." (PMID 28296140, 2017). "The amplification of PIK3CA, PTEN, KRAS, SOX2, DVL3, and TP63 were present in all tumor samples in M7 and M9, including N4 in M7." (PMID 29050228, 2017). "As with cetuximab, the research on panitumumab focused on other targets in addition to RAF and RAF, such as PIK3CA and PTEN, that activate tumor cell proliferation and migration, as well as invasion and neovascularization in mCRC." (PMID 28708103, 2017). "The clinicopathologic variables compared with FBXW7 status included age, sex, race/ethnicity, site of the primary tumor, histologic grade, and KRAS, NRAS, BRAF, PIK3CA, and microsatellite instability status." (PMID 28424412, 2017). "NIH-III mice with PIK3CA-mutant NCI-H460 tumors were treated with a single dose of SN32976 and plasma and tumor were collected at multiple timepoints after dosing for pharmacokinetic analysis and evaluation of pAKT expression." (PMID 28537878, 2017). "In patients in which tumor markers CA15-3 and CEA and PIK3CA mutant DNA fluctuated in the same way, Pearson correlation coefficients ranged from 0.99 to 0.46 and from 0.99 to 0.38 respectively (mean 0.82 for CA 15–3 and 0.79 for CEA)." (PMID 28330468, 2017). "This observed anti-tumor effect was more pronounced with the miRNAs than with targeted silencing of the EGFR and PIK3CA proteins using validated siRNAs." (PMID 27095166, 2016). "Among all the 702 hotspots, we found that 68 were highly prevalent in one tumor type, 11 in two tumor types, 2 (KRAS G12 and PIK3CA E542) in three tumor types, and 1 (KRAS G13) in four tumor types." (PMID 27356755, 2016). "In a preclinical study using a genetically engineered mouse model carrying wild-type PIK3CA with CRC, NVP-BEZ235 induced tumor regression." (PMID 27242542, 2016). "PD-L1 expression in tumor cells correlated significantly with gender, tumor localization, Laurén and mucin phenotype, UICC-stage, lymph node ratio, EBV-, MSI-, Her2/neu- and PIK3CA-status." (PMID 27009855, 2016). "In addition, PIK3CA (H1047R) mutation was more frequently detected in non-recurrent tumors (5 out of 6 cases; P = 0.077) and only 1 tumor with local recurrence, whereas tumors with regional recurrence or distant metastasis did not harbor PIK3CA (H1047R) mutation." (PMID 27119232, 2016).
tumor (continued). "EGFR activation elicits its effects partially via PIK3CA/AKT/mTOR pathways, which promote tumor proliferation, invasion, and migration." (PMID 27554588, 2016). "For example, alterations in PIK3CA and ARID1A were early events in tumour S13T2 (clonality >60%), but were detectable in <35% of cells in S13T1." (PMID 27377421, 2016). "PIK3CA mutation status did not predict the benefit of addition of pictilisib to fulvestrant either, but this was based on archived tumor specimens, which may not reflect the latest mutation status and underscores the fact that PI3K genotype may not be the most reliable biomarker of response." (PMID 26779371, 2015). "Additionally, we assessed the anti-tumor activity of ARQ 092 in in vivo mouse models implanted with AN3CA cells (mutant PIK3R1, PTEN deficient, and activating mutation of FGFR2), KPL-4 cells (over-expression of HER2 and mutation in PIK3CA); and ZR-75-1 cells (ER positive, PTEN deficient)." (PMID 26469692, 2015). "Transfection of ca-PIK3CA, ca-AKT, or dnFOXO1 into newborn DKO mouse retinas each led to striking tumor formation, with many Ki-67-positive cells, at 60 days of age (n = 5)." (PMID 25907958, 2015). "In mice bearing HER2-amplified wild-type PIK3CA xenografts, dual HER2 targeting with trastuzumab and lapatinib resulted in tumor regression." (PMID 24451154, 2014). "In a PIK3CA-mutant HER2+ xenograft, PI3K inhibition with BKM120 in combination with lapatinib and trastuzumab was required to achieve tumor regression." (PMID 24451154, 2014). "Based on current knowledge on the mutation load of human tumors, it is likely that yet unidentified oncogenes - different from FGFR3, PIK3CA, and RAS - and tumor suppressors participate in UBC." (PMID 23650517, 2013). "We correlated the KRAS, BRAF and PIK3CA genotypes with clinicopathological features of CRC, including primary tumour location, histological findings, and sites of metastases." (PMID 23617638, 2013). "When we examined PIK3CA and PTEN mRNA expression in different strata of the study population: By oestrogen receptor status, HER2 status, and by tumour histology, results were similar." (PMID 24083111, 2013). "The SOX2 and PIK3CA genes both reside on the long arm of chromosome 3 (3q26) and these genes were amplified in three HPV+ samples and one HPV- tumor." (PMID 23718828, 2013). "Indeed, knockdown studies confirmed that targeting the glycolytic pathway for disruption results in anti-proliferative effects, specific to PIK3CA mutant cells, suggesting that this could be a therapeutic strategy for specifically targeting patients with PIK3CA mutant tumours." (PMID 23028762, 2012). "Fluorescent in situ hybridisation analyses of PTEN, PIK3CA, EGFR and CEN7 were performed on tumour specimens from patients treated on the expanded access gefitinib trial." (PMID 22095222, 2011). "Moreover, because we concurrently assessed clinical, pathologic and tumor molecular variables such as the CpG island methylator phenotype (CIMP), LINE-1 methylation, KRAS, BRAF and PIK3CA mutations, we could evaluate the effect of TGFBR2 or BAX mutation independent of these potential confounders." (PMID 21949851, 2011).